IBA57 (iron-sulfur cluster assembly factor IBA57)
Description:
Mitochondrial protein involved in the maturation of mitochondrial [4Fe-4S]-proteins in the late stage of the iron-sulfur cluster assembly pathway. Operates in cooperation with ISCA2 in the maturation of [4Fe-4S] proteins. Involved in the maturation of mitochondrial 2Fe-2S proteins in the late stage of the iron-sulfur cluster assembly pathway.
Synonyms: C1orf69; FLJ12734; MMDS3; SPG74
Tractability: Small molecule: a structure with a bound ligand is known. PROTAC: its protein half-life has been measured.
Gene: Protein-coding gene on chromosome 1 (228,165,777 to 228,182,257, forward strand). Ensembl gene ENSG00000181873.
Subcellular location: Mitochondrion
Subcellular location (Human Protein Atlas): Mitochondria
Gene Ontology:
Molecular function: protein binding; RNA binding
Biological process: protein maturation
Cellular component: iron-sulfur cluster assembly complex; mitochondrion
Genetic constraint (gnomAD): Loss-of-function variants: 20 observed, 15.58 expected, observed/expected ratio (o/e) 1.28, 90% interval 0.9 to 1.8. The synonymous counts are far from expectation, so gnomAD's model fits this gene poorly and the ratio says little. Missense variants: 608 observed, 438.65 expected, observed/expected ratio (o/e) 1.39, 90% interval 1.3 to 1.48. Synonymous variants: 310 observed, 201.9 expected, observed/expected ratio (o/e) 1.54, 90% interval 1.4 to 1.69.
Gene-disease validity (ClinGen):
ClinGen rates the evidence that IBA57 causes each of these diseases.
mitochondrial disease (autosomal recessive): Definitive.
Homologues: Orthologues: chimpanzee IBA57 (99% identical), dog IBA57 (76% identical), mouse Iba57 (70% identical), guinea pig IBA57 (69% identical), rat Iba57 (69% identical), macaque IBA57 (45% identical), tropical clawed frog iba57 (45% identical), zebrafish iba57 (42% identical), Drosophila melanogaster CG8043 (31% identical), Caenorhabditis elegans F39H2.3 (23% identical).
Diseases named in the same sentence as IBA57 in open-access papers:
IBA57 is named in the same sentence as 18 diseases in open-access papers, as found by Europe PMC text mining. Sharing a sentence is not in itself a finding about the gene and the disease. The quoted sentences say what the papers report.
multiple mitochondrial dysfunctions syndromes (5 papers, 2015 to 2023). "Mutations in ISCA2 and IBA57 genes have been reported in patients affected by multiple mitochondrial dysfunctions syndromes (MMDS), specifically MMDS3 for IBA5722–28 and MMDS4 for ISCA229,30." (PMID 31831856, 2019). "Defects in ISCA1, ISCA2 and IBA57 have been associated with numerous mitochondrial diseases now categorized as multiple mitochondrial dysfunctions syndromes MMDS3 (IBA57), MMDS4 (ISCA2), and MMDS5 (ISCA1)." (PMID 30200358, 2018). "Second, mutations in human IBA57 have been implicated in neurological diseases such as spastic paraplegia 74 (OMIM 615316) and multiple mitochondrial dysfunctions syndrome 3 (MMDS3, OMIM 615330)." (PMID 37588046, 2023). "Genetic defects in NFU1 (causing MMDS1, OMIM #605711), BOLA3 (causing MMDS2, OMIM #614299), and IBA57 (causing MMDS3, OMIM #615330), all factors acting in the final step of the assembly of [4Fe–4S] proteins, have been designated multiple mitochondrial dysfunction syndromes (MMDSs)." (PMID 25918518, 2015). "In contrast, mutations in late acting mitochondrial ISC genes such as ISCA1-ISCA2 and IBA57 usually lead to multiple mitochondrial dysfunction syndrome and do not cause iron dysregulation because of their non-involvement in extramitochondrial Fe-S protein metabolism." (PMID 34732213, 2021). "Defects in protein components of the mitochondrial ISC machinery are associated with numerous diseases, including Friedreich ataxia (defects in frataxin), myopathy (defects in ISCU or FDX2), and multiple mitochondrial dysfunction syndromes (defects in NFU1, BOLA3, ISCA2, and IBA57)." (PMID 30200358, 2018).
leukodystrophy (2 papers, 2022 to 2023). Leukodystrophies are a group of rare, progressive, metabolic, genetic diseases that affect the brain, spinal cord and often the peripheral nerves. "Human patients with an IBA57 deficiency suffering from a leukodystrophy-like phenotype were first described in 2013." (PMID 37588046, 2023).
Multiple mitochondrial dysfunctions syndrome type 3 (2 papers, 2022 to 2024). "Multiple mitochondrial dysfunctions syndrome type 3 (MMDS3) is a rare autosomal recessive mitochondrial leukoencephalopathy caused by biallelic pathogenic variants in the IBA57 gene." (PMID 39408793, 2024). "Biallelic pathogenic variants in the IBA57 gene have been shown to cause a spectrum of diseases, including multiple mitochondrial dysfunction syndrome type 3 (MMDS3) in 52 patients as well as a SPOAN (OMIM# 609541)-like phenotype in 11 members of a single family." (PMID 36360281, 2022).
Encephalopathy (1 paper, 2024). Encephalopathy is a term that means brain disease, damage, or malfunction. "The mitochondrial YgfZ ortholog (IBA57) is implicated in the synthesis of Fe/S proteins and mutations in the IBA57 gene have been linked with hereditary spastic paraplegia and a metabolic syndrome presenting with severe myopathy and encephalopathy." (PMID 38531971, 2024).
leukoencephalopathies (1 paper, 2018). "It is also a quite common finding in Iron-sulfur cluster related leukoencephalopathies, particularly those caused by GLRX5, ISCA2, or IBA57 mutations." (PMID 29615062, 2018).
cancer (2 papers, 2022). A tumor composed of atypical neoplastic, often pleomorphic cells that invade other tissues. "Targeting genes such as NDUFS1, NFU1, or IBA57 is therefore a potential route for selectively killing cancer cells in acidic microenvironments." (PMID 35263578, 2022).
IBA57 also shares sentences with these, for which no sentence is quoted: anemia (1 paper); genetic disorders (1); hereditary spastic paraplegia (1); kidney cancer (1); lactic acidosis (1); metabolic syndrome (1); mitochondrial disease (1); myopathy (1); neurological diseases (1); renal clear cell carcinoma (1); respiratory failure (1); tumor (1).